SCARNA23 (small Cajal body-specific RNA 23)
Synonyms: ACA12
Gene: Small Cajal body-specific RNA gene on chromosome X (24,744,441 to 24,744,570, forward strand). Ensembl gene ENSG00000251869.
Gene Ontology:
Biological process: RNA processing
Cellular component: Cajal body; nucleolus
Homologues: Paralogues in human: SCARNA22 (34% identical).
Diseases named in the same sentence as SCARNA23 in open-access papers:
SCARNA23 is named in the same sentence as 1 disease in open-access papers, as found by Europe PMC text mining. Sharing a sentence is not in itself a finding about the gene and the disease.
SCARNA23 shares sentences with these, for which no sentence is quoted: pulmonary arterial hypertension (1 paper).